RNU6-864P (RNA, U6 small nuclear 864, pseudogene)
Gene: Small nuclear RNA gene on chromosome 14 (28,982,303 to 28,982,410, reverse strand). Ensembl gene ENSG00000252065.
Homologues: Orthologues: chimpanzee U6 (94% identical), macaque U6 (87% identical), guinea pig U6 (62% identical), dog U6 (54% identical). Paralogues in human: RNU6-1122P (71% identical), RNU6-1237P (71% identical), RNU6-574P (71% identical), RNU6-1029P (70% identical), RNU6-329P (70% identical), RNU6-333P (70% identical), RNU6-38P (70% identical), RNU6-657P (70% identical), RNU6-658P (70% identical), RNU6-883P (70% identical), RNU6-1020P (69% identical), RNU6-140P (69% identical), and 1285 more.